IL2 (interleukin 2)
Diseases named in the same sentence as IL2 in open-access papers (continued):
Sharing a sentence is not in itself a finding about the gene and the disease.
Salmonella Infections (10 papers, 2009 to 2024). Infections with bacteria of the genus SALMONELLA. "As studied in mice infection model, the mechanisms employed by IFN-γ, IL-2 and IL-6 for establishing protection against Salmonella infection are diverse in nature." (PMID 28143524, 2017). "We have further shown that IFN-γ can activate in vitro heterophil functional activity against Salmonella and the presence of IFN-γ and IL-2 in a S. Enteritidis immune cytokine cocktail protects day-old chicks against Salmonella infections mediated by activated heterophils." (PMID 35846741, 2022). "The main factor of CD4+ T cell help seems to be IL-2, since replacement of CD4+ T cell help by addition of IL-2 is sufficient to elicit CD8+ T cell proliferation, induced by Salmonella infection of the B cells." (PMID 20885961, 2010). "The preincubation of DCs with LP-treated-EC supernatants prior to Salmonella infection, drastically reduced the DC's ability to activate T cells and drive their polarization to Th1 T cells as evidenced by a decrease in IFN-γ, IL-2 and IL-6 production." (PMID 19756155, 2009). "Thus, polyfunctional CD4+ T cells that develop during Salmonella infection produce simultaneously IFN-γ, TNF and IL-2 and the differential amounts of IFN-γ that is being produced by these cells correlates with the immunodominance hierarchy." (PMID 22912884, 2012).
soft tissue sarcoma (10 papers, 2013 to 2025). A malignant neoplasm arising from muscle tissue, adipose tissue, blood vessels, fibrous tissue, or other supportive tissues excluding the bones. "This approach was evaluated in a canine clinical trial that showed reprogramming of the TME in canine soft tissue sarcomas by IL-2 and IL-12 linked to lumican." (PMID 38063196, 2023). "Notably, reduced ALC is strongly associated with higher serum concentrations of IL-6 and IL-2 in patients with soft tissue sarcoma." (PMID 41568390, 2025). "In fact, decreased ALC significantly correlates with increased serum levels of IL-6 or IL-2 in patients with soft tissue sarcoma." (PMID 31217896, 2019). "One of the three patients with soft tissue sarcoma-treated IL-2-transfected xenogeneic cells (Vero-IL-2) showed durable reduction of two distant, noninjected metastases." (PMID 30158830, 2018). "Inducing one week of daily cyclic high fever response during individually dose adapted IL-2 we are in the footsteps of William B. Coley, the father of cancer immunotherapy who administered an FDA-approved fever inducing bacterial inoculate for the treatment of soft tissue sarcomas." (PMID 33151369, 2021).
T-cell leukemia (10 papers, 2005 to 2021). A malignant disease of the T-lymphocytes in the bone marrow, thymus, and/or blood. "Adult T-cell leukemia cells in the majority of ATL patients appeared unresponsive to IL-2; however, eight IL-2-dependent ATL cell lines were established from five patients out of 26 ATL patients." (PMID 32210945, 2020). "Jurkat is a T cell leukemia-derived cell line that retains its original T-helper properties with regard to surface antigen expression and inducibility of the IL-2/IL-2Rα positive feedback loop." (PMID 28234966, 2017). "The combination of IL-2 growth of T cells with sensitive RT assays would be (and still is) the key to the discoveries of human retroviruses in T cell leukemias and AIDS." (PMID 15743526, 2005). "Persistent IL-2-regulated HHV-6 infection of adult T-cell leukemia cells causes T-cell leukemia to progress more rapidly, but in vivo studies have not yet confirmed a pathogenetic role for HHV-6 in this disease." (PMID 22110893, 2011). "Adult T-cell leukemia cells express IL-2Rα constitutively, which made it possible to establish eight leukemic and 24 non-leukemic T-cell lines growing dependently on IL-2 from the PBMCs of 26 ATL patients using IL-2." (PMID 32210945, 2020). "Interestingly, IMiDs-driven downregulation of IKZF1/IKZF3 is rather non-toxic to T-cells or T-cell leukemias but results in increased expression of interleukin 2 (IL-2) and decreased expression of tumor necrosis factor alpha (TNF-α) in monocytes." (PMID 31487824, 2019).
thyroiditis (10 papers, 1990 to 2025). Inflammation of the thyroid gland. "Moreover, TSH itself can act as a cytokine in thyroid diseases and is associated with the continuous release of IL-1, IL-2, IL-6, and IL-12 by lymphocytes and dendritic cells, further enhancing immune responses and mast cell activation." (PMID 40075855, 2025). "Baseline serum cytokine concentrations of IL-1β, IL-2, and GM-CSF were elevated in patients with thyroid related adverse reactions in a study of multiple solid tumors receiving immunotherapy." (PMID 36091125, 2022). "In addition to the mild transient facial edema, the only classic IL-2 immune-related AE was thyroiditis." (PMID 25622640, 2015). "We observed that stimulation of PBMCs with CpG-B and IL-2 led to the production of IgG anti-thyroperoxidase and anti-cardiolipin antibodies from the majority of patients with thyroiditis (3 out of 4 patients) and anti-phosphoslipid antibody syndrome respectively (2 out of 3 patients)." (PMID 18625057, 2008). "The main possible mechanisms underlying this phenomenon are as follows: (a) IL-2 and IFN-γ may participate in the thyroid autoimmune process and affect thyroid function by blocking the PD-1/PD-L1 pathway; (b) IFN-γ and TNF-α produced by Th1 cells induce the release of CXCL10 from thyroid cells." (PMID 37051293, 2023). "The radiation dose regimen was identical to the FORCE trial (5 × 4 Gy), and no toxicity was observed that could not be explained by the safety profile of Interleukin-2 (e.g. grade I-II thyroiditis in 25% of study subjects)." (PMID 31703637, 2019).
Behçet’s disease (9 papers, 2012 to 2025). "Providing cytotoxicity which immunosuppressants can bring, the low-dose IL-2 can be considered a new-type and effective treatment for Behçet’s disease and is relatively safer." (PMID 36281176, 2022). "It is known that JAK1/STAT3 signaling pathway is activated in some systemic vasculitides (Behcet disease) through the activation of Th1/Th17-type cytokines such as IL-2, interferon (IFN-γ), IL-6, IL-17, and IL-23 but its role in KD is not well-understood." (PMID 33692975, 2021).
chlamydial infection (9 papers, 2012 to 2024). "It has been shown that during chlamydial infection, the level of IL-2 production is much higher in response to stimulation with inactivated C. muridarum than in response to the rTC_0037 protein." (PMID 38396724, 2024). "Reportedly T-cells co-expressing TNF-α/IL-2/IFN-γ elicit heightened protection against a genital chlamydial challenge, which provides additional evidence for the protective role of IFN-γ and IL-2 in chlamydial infections." (PMID 30374357, 2018). "Though not significant, these neonates also presented with elevated IL-2, IL-10, and IL-13 when compared to adult mice, showing that chlamydial infection alone was enough to elicit a Th2-like response." (PMID 24376704, 2013). "In an attempt to mimic chronic chlamydial infections, Macaca nemestrina fallopian tubes received repeated C. trachomatis infections, which resulted in fibrosis and elevated IL-6, IL-10, IL-2, and IFNγ levels." (PMID 22894815, 2012). "We also detected an increase of MIF/GIF after chlamydial infection, a pro-inflammatory cytokine promoting the production of tumor necrosis factor (TNF), IFN-γ, IL-1β, IL-2, IL-6 and IL-8." (PMID 25019934, 2014). "The relative increase in production of important cytokines (TNF-α, IL-6, IL-2 and INF-γ) in the AHCC-fed group may lead to decreased chlamydia genital infection in the stress model." (PMID 27790645, 2015). "Chlamydial infection in neonatal mice induced increased production of Th2 cytokines (IL-4, 5, 10, and 13) in both BAL and serum, while infected adult mice produced increased Th1 cytokines (IL-2, IFN-γ)." (PMID 24376704, 2013). "Again, there was no change detected in IL-2, IL-4, IL-12 or IL-17α due to chlamydial infection in any of the mice (data not shown)." (PMID 23189195, 2012).
chronic hepatitis C (9 papers, 2012 to 2023). "In another study, chronic hepatitis C patients presented elevated serum levels of IL-10, IFN-γ, IL-6, and IL-4, while IL-1, IL-2, IL17, IL-22, IL-13 TNF, IL-12p70, and IL-15 levels were lower in patients compared to healthy controls." (PMID 29977152, 2018). "This is an important finding since some studies have shown that the largest proportion of cellular infiltrate found in a liver with chronic hepatitis C is TH1 cells, such as IL-1b, IL-2, IL-6, IL-8, TNF-α and IFN." (PMID 22830036, 2012). "In chronic hepatitis C, a decrease in IL-2 appears to be chiefly responsible for the lack of activation of virus-specific CD4+ T cells." (PMID 34832674, 2021). "We assessed whether the impaired functionality of HCV-specific CD4+ and CD8+ T cells manifested by reduced T helper 1 cytokine production (IL2 and IFN-Ɣ) during chronic hepatitis C is restored upon HCV clearance with DAA treatments." (PMID 34242330, 2021).
esophageal cancer (9 papers, 2010 to 2024). A primary or metastatic malignant neoplasm involving the esophagus. "In esophageal cancer, miR-503 can induce the loss of interleukin-2 and interferon-γ expression, therefore enhancing the proliferation and invasion of tumor cells." (PMID 39456192, 2024). "Interleukin 2 (IL-2) has been used to treat diverse types of cancer that express the IL-2 receptor (IL-2R) such as intestinal cancer, esophageal cancer, and head and neck cancer." (PMID 31662754, 2019). "In the current study, we demonstrated that serum concentrations of IL-2 and IFN-γ were positively associated with local response to radiotherapy in esophageal cancer." (PMID 24967419, 2014). "We found that serum concentrations of IL-2 and IFN-γ were positively associated with local response to radiotherapy in esophageal cancer." (PMID 24967419, 2014). "The correlations between the changes in the serum concentrations of IL-2 and IFN-γ during radiotherapy for esophageal cancer and treatment outcomes were investigated." (PMID 34488754, 2021). "In the present study, we have provided such evidence, specifically detailing correlations between radiotherapy outcomes and changes in the serum IL-2 and IFN-γ concentrations during radiotherapy for esophageal cancer." (PMID 24967419, 2014). "In the present study, we sought to provide such evidence, specifically investigating correlations between radiotherapy outcomes and changes in the serum IL-2 and IFN-γ concentrations during radiotherapy for esophageal cancer." (PMID 24967419, 2014).
HCMV infection (9 papers, 2013 to 2026). "Expression of IL2 significantly decreased in case of group 1 and group 2 patients i.e. those with active HCMV infection than group 3 patients." (PMID 32985571, 2020). "The inhibition of the HCMV infection of IL-26-treated fibroblasts of about 50% was further quantified by flow cytometry in comparison to the control protein IL-2." (PMID 23875025, 2013). "To investigate the immunomodulatory effects of treatment with Tα1 + PCDs in CD4+ and CD8+ T cells during HCMV infection, we evaluated the expression of CD2 and CD40L, as well as the production of TNFα, IFNγ and IL-2 using multiparametric cytometry." (PMID 38396631, 2024). "In infections with persistently low antigen concentrations, e.g., latent asymptomatic cytomegalovirus infection, CD4+ T-cells secreting IFN-γ only, IFN-γ/IL-2, or IL-2 only are detected." (PMID 25729380, 2015). "An analysis of seven infants with congenital CMV infection showed a lack of production of IFN-γ, IL-2, and IL-4 from CD4+ T cells on exposure to pp65-derived peptide." (PMID 32509591, 2020). "The control proteins GST and IL-2 used for VSV and HCMV infection, respectively, did not influence the resulting virus titers from infected fibroblasts or Colo-205 cells." (PMID 23875025, 2013).
head and neck squamous cell carcinoma (9 papers, 1994 to 2025). A squamous cell carcinoma that arises from any of the following anatomic sites: lip and oral cavity, nasal cavity, paranasal sinuses, pharynx, larynx, and salivary glands. "The combination of HER2/neu CAR-T cells and oncolytic adenovirus-expressing anti-PD-L1 and IL-2 remarkably improved survival compared with monotherapy in head and neck squamous cell carcinoma xenograft mice." (PMID 37660142, 2023). "The efficacy of ten daily injections of 500 or 500,000 U of recombinant interleukin 2 (IL-2) day-1 given 1.5 cm from the insertion of the sternocleidomastoid muscle on the mastoid was evaluated in 31 patients with recurrent head and neck squamous cell carcinoma." (PMID 8123489, 1994). "In head and neck squamous cell carcinoma, PD-L1 binds to ILF3 and IL2 to activate STAT3 for PD-L1 signaling to promote tumor progression." (PMID 40140647, 2025). "In a preclinical model of head and neck squamous cell carcinoma (HNSCC), MUC1-CAR-T cells specifically killed MUC1+ HNSCC cell lines in vitro and secreted IL-2, interferon γ (IFN-γ), and TNF-α." (PMID 38727261, 2024). "ALDH1-positive head and neck squamous cell carcinoma cells inhibited T-cell proliferation more efficiently than ALDH1-negative cells, and inhibited cytokine, interferon γ (IFN-γ), Interleukin-2 (IL-2) and tumor necrosis factor α (TNF-α)." (PMID 36497050, 2022).
hepatitis C (9 papers, 2010 to 2025). "Additionally, some research highlighted that patients with chronic hepatitis B had a Th1 response with higher levels of IFN-γ, TNF-α, and IL-2, when compared to patients with hepatitis C and healthy individuals." (PMID 40559733, 2025).
Infertility (9 papers, 2012 to 2025). "IL-2 concentrations are closely associated with Testosterone hormone levels in COVID-19 infertile patients." (PMID 40070583, 2025). "The molecules most involved in infertility are interleukin (IL) -1, IL-2, IL-6, IL-8, interferon-ɣ, and tumor necrosis factor-α (TNF-α)." (PMID 33925640, 2021). "Moreover, unexplained infertile patients have demonstrated elevated levels of serum IL-2, IL-4, IL-6, IL-21, tumor necrosis factor alpha (TNF-α), and IFN-γ, compared with fertile women." (PMID 30546347, 2018). "The increase in IL-2 and IL-4 production by whole sperm cells-stimulated PBMCs of infertile patients with ASA, as compared to controls, could create the environment that lead to generation of Th2-type of response and resulting in antibody production." (PMID 22952917, 2012). "It has been reported that the levels of IL-2, IL-6, IL-10 and TGFB1 in seminal plasma or serum are significantly elevated in infertility patients compared to healthy controls." (PMID 31855573, 2019). "Recent studies have shown that immunocompetent cells in the blood of PCOS patients with infertility in vitro produce several cytokines, including IFN-γ, TNF-α, and IL-2, which may be involved in chronic inflammation." (PMID 38911246, 2024). "Recent studies have shown that several cytokines, including IFN-γ, TNF-α, IL-2, IL-4, IL-5, and IL-10, were produced by immunocompetent cells in the blood from PCOS with infertility in vitro, which might be involved in chronic inflammation." (PMID 30988342, 2019).
nasal polyps (9 papers, 2010 to 2023). "The present research is the first study to evaluate the role of IL-1RN, IL-2, and IL-4 gene polymorphisms in a Turkish population with nasal polyposis." (PMID 31650822, 2019). "Additionally, elevated IL-2 levels may contribute to an increased risk of Nasal Polyps (NP), whereas higher levels of PDGF-BB might be associated with a reduced risk of NP." (PMID 38022554, 2023). "SEB resulted in a significant release of IL-1, TNF-α, IFN-γ, Il-2, IL-5 and IL-17 from nasal polyp tissue, indicating the stimulation of all prominent T helper cell populations." (PMID 22272213, 2012). "SEB induced a significantly higher release of TNF-α and IL-2 in nasal polyps from AERD patients after 4 hours of stimulation." (PMID 23282714, 2010). "There is a positive correlation between levels of IL-2 and proportion of Treg cells in nasal polyps, indicating that the decreased number of Treg cells in nasal polyps may result from the downregulation of IL-2 signaling pathway." (PMID 35008843, 2021). "The levels of IL-2 measured by ELISA are decreased in nasal polyps compared to control tissue." (PMID 35008843, 2021). "Stimulation of nasal tissue explants originating from inferior turbinate or nasal polyp tissue with the superantigen SEB for 24 hours stimulated the release of TH1 and Th 2 cytokines (IFN-γ, IL-2, IL-4, IL-5, IL-10, and IL-13)." (PMID 23282714, 2010). "Similarly, nasal polyp tissue displays a SEB-stimulated significant release of IL-1, TNFα, IFN-γ, IL-2, IL-5 and IL-17." (PMID 25875480, 2015). "After 18 hours, SEB significantly induced the release of TNF-α, IFN-γ, IL-2, and IL-5 in both nasal polyp-asthma groups compared with healthy controls but without statistical differences between disease groups." (PMID 23282714, 2010).
Parkinson disease (9 papers, 2010 to 2022). A progressive degenerative disorder of the central nervous system characterized by loss of dopamine producing neurons in the substantia nigra and the presence of Lewy bodies in the substantia nigra and locus coeruleus. "In murine models of neurodegenerative Parkinson’s disease, the intrathecal graft of hDPSCs ameliorated behavioral deficits and dopaminergic (DA) neuron loss, by upregulating anti-inflammatory cytokines IL2, IL4, and TNF-β and reducing IL-1α, IL- 1β, IL6, IL8, and TNF-α pro-inflammatory ones." (PMID 33805573, 2021). "Furthermore, greater disease severity, whether measured for cognition or parkinsonism, was associated with lower levels of IL-1beta, IL-2 and IL-4, further supporting our finding that inflammatory markers decrease with disease progression." (PMID 29248892, 2018). "Biofluid studies also support the role of neuroinflammatory processes in Parkinson's disease, with elevated levels of IL-2, IL-6, and TNF-α in the serum of patients with PD." (PMID 34725564, 2021). "Female patients with Parkinson’s disease (PD) showed elevated levels of IL-1α, IL-2 and IL-6 while male patients with PD showed elevated levels of only IL-4 compared to healthy controls." (PMID 28196514, 2017). "We investigated whether low-dose interleukin 2 (IL-2) expands Treg populations and protects nigrostriatal dopaminergic neurons in a model of Parkinson’s disease (PD)." (PMID 38407500, 2022). "At this timepoint, an early pro-inflammation was observed in vehicle-treated hαSyn Parkinson’s disease mice with elevated percentages of CD8+CD69+ T cells in brain and increased levels of interleukin-2 (IL-2) in the cervical lymph nodes and spleen." (PMID 36587195, 2022).
renal dysfunction (9 papers, 2010 to 2024). "In summary, induction therapy with low doses of ATG or anti-IL2 antagonists in cirrhotic patients with pretransplant renal dysfunction are good strategies for preserving posttransplant renal function, with the cost of ATG being much lower." (PMID 30186817, 2018). "Renal dysfunction, based on serum creatinine increase, was associated with an increase in total bilirubin, direct bilirubin, GOT and with a pro-inflammatory cytokine profile including IL-2, IL-1β, IL-17A and IL-8." (PMID 36178979, 2022). "Furthermore, severe toxicities were observed as a result of high‐dose IL‐2, which induces a vascular permeability leak that leads to fluid retention and interstitial edema, and results in circulatory failure, lung edema, and renal dysfunction." (PMID 30003192, 2018).